EGFR (epidermal growth factor receptor)
Diseases named in the same sentence as EGFR in open-access papers (continued):
Sharing a sentence is not in itself a finding about the gene and the disease.
breast carcinoma (continued). "In particular, when GE11-positive exosomes containing the TS miRNA, let-7a, were administered to EGFR-expressing breast cancer xenograft tumor-bearing mice, these GE11-positive let-7a-loaded exosomes were observed to not only target the tumors, but also impair their development." (PMID 35954176, 2022). "Such EGFR-bypass signalling mechanisms have been linked to drug resistance in cancer cells in the past, and increased levels of OTR might also contribute to such resistance development for EGFR-targeted treatment in breast cancer patients." (PMID 35884900, 2022). "Taken together, these findings suggest the co-existence of two independent molecular mechanisms able to trigger aerotaxis in breast cancer cell lines, one dependent on the classical EGFR activity, and one relying on another mechanism that remains to be identified." (PMID 36380366, 2022). "Since vandetanib may provide a therapeutic effect in luminal breast cancer, AP-2γ may also be used to predict the response to vandetanib treatment, together with epidermal growth factor receptor and RET." (PMID 36197225, 2022). "We hypothesized that the silencing of EGFR expression using a specific siRNA might reduce the proliferation and growth of breast cancer cells and be beneficial for exerting antitumour activity." (PMID 36412852, 2022). "Moreover, we docked the phytochemicals and examined their binding affinities with EGFR, PR and NF-κB proteins, which are overexpressed in breast cancer." (PMID 36144225, 2022). "For instance, IMP-1710 could be useful to study the role of UCHL1 in other cancer contexts where UCHL1 is known to regulate EGFR expression, such as in EGFR+ colorectal cancers, drug-resistant breast cancer and thyroid and glioma carcinomas." (PMID 34497382, 2022). "Additionally, the combination treatment with Se/FO and chemotherapeutic agents increases the efficacy of EGFR inhibition in the tumor tissues of mammary tumor-bearing mice." (PMID 36547898, 2022). "In addition, 3-methylcholanthrene has been reported to activate EGFR/ERK/c-Fos transduction signaling through an Aryl hydrocarbon Receptor (AhR) and GPER-mediated mechanism in both breast cancer cells and Cancer-Associated Fibroblasts (CAFs)." (PMID 34831222, 2021). "The epidermal growth factor receptor (EGFR) ligand amphiregulin (AREG) is shown to be required for YAP-induced proliferation in breast cancer cells, thus suggesting that EGFR signaling is an important YAP effector, regulating both physiological and malignant cell proliferation." (PMID 34439395, 2021). "For example, the anti-epidermal growth factor receptor (EGFR), HER2 and vascular endothelial growth factor (VEGF) antibodies or peptides have been linked to liposomal system to deliver doxorubicin or other medicines to breast cancers and other tumors." (PMID 34359650, 2021). "Furthermore, the overexpression of EGF, a potent mitogen, and its related receptor, EGFR, is a common feature in breast cancer, regulating the MAPK activity pathway." (PMID 34298639, 2021). "Rac inhibition may represent a viable strategy for treatment of EGFR/HER2 targeted therapy resistant breast cancer." (PMID 34074257, 2021). "HDAC inhibition by SAHA in estrogen receptor α (ER)-negative breast cancer cells has been associated with lower EGFR expression due to a reduction in its mRNA stability." (PMID 33976119, 2021). "EGFR was highly expressed in 18.1% (29/160) of 160 breast cancer tissue samples." (PMID 34591414, 2021). "E2 binds GPER1 with high affinity and this activation leads to ERK phosphorylation, PI3K stimulation, intracellular Ca2+ increase, and cAMP production in the MCF-7 breast cancer cell line, which occurs via trans-activation of the epidermal growth factor receptor and results in proliferation." (PMID 34089761, 2021). "Also in adult patients, tumor mutations, such as in EGFR, BRCA1/BRCA2, and SMAD4 genes, decrease engraftment rates in adenocarcinoma, breast cancer, and pancreatic cancer, respectively." (PMID 33837665, 2021).
breast carcinoma (continued). "Therefore, for the remainder of this section, we will focus on molecular recognition of EGFR by DHHC20, the DHHC family member most biologically relevant to EGFR regulation in lung and breast cancer." (PMID 34610265, 2021). "In addition, expression of cytokeratin 5/6 and EGFR are major factors in defining the basal-like subtype of breast cancer and further decrease the already abysmal prognosis of this aggressive form of disease." (PMID 33128042, 2021). "Consequently, Rac plays a significant role in resistance to EGFR/HER+ breast cancer by acting downstream of EGFR/HER2 therapy resistance mechanisms such as Ras/MAPK and PI3-K/Akt signaling." (PMID 34074257, 2021). "In addition, our results suggest that the HOXB7 role in breast cancer is strictly dependent on the cellular genetic background, especially regarding ER, EGFR, and HER2 expression, along with the modulation of the levels of this transcription factor." (PMID 34063128, 2021). "Moreover, targeted proteins relating to breast cancer such as ERα, PR, EGFR, HER2, Pgp, and NF-κB were analyzed for impact after being treated with MUC-30 by the estimation of IC50 values calculated by AutoDock." (PMID 34135981, 2021). "Furthermore, PL was found to target the human epidermal growth factor receptor (HER) family in breast cancer, which plays a major role in controlling the intracellular signaling pathways." (PMID 36046754, 2021). "In addition, many studies have suggested that estrogen positive premenopausal breast cancer has distinct molecular characteristics compared to postmenopausal cancers and behaves differently with distinct integrin/laminin and EGFR signalling pathways." (PMID 34659834, 2021). "Crosstalk between Wnt and EGFR has been identified in many tumors including breast cancers." (PMID 34564708, 2021). "Previous results have indicated that loss of SHP-1 might serve as a biomarker for the application of TKIs in patients with breast cancer, and these patients might achieve additional benefit from therapy targeted against EGFR." (PMID 34591414, 2021). "EGFR could alter TGF-β function from antitumorigenic to protumorigenic in breast cancer 68, while TGFB1 increased fibrogenic gene expression and myofibroblast differentiation." (PMID 34326696, 2021). "High expression of EGFR is known to correlate with poor clinical outcome in breast cancer." (PMID 34165702, 2021). "Such pathways may work synergistically with other NO pathways in breast cancer, such as the epidermal growth factor receptor (EGFR)-mediated activation of ERK." (PMID 33513777, 2021). "Epidermal growth factor receptor (EGFR) is highly expressed on the surface of breast cancer cells." (PMID 34209892, 2021). "EGFR has been identified to be regulated by MYOF in breast cancer." (PMID 34957301, 2021). "In summary, our current results revealed that SHP-1 significantly inhibits breast cancer cell proliferation and cell invasion and suppresses mammary tumorigenesis in xenografts in mice by directly interacting with EGFR and inhibiting the EGFR/Ras/Erk/GSK3β signaling pathway." (PMID 34591414, 2021). "High expression of EGFR is frequently associated with TNBC, and we previously identified a correlation between high PKCδ expression and overall decreased survival of luminal A breast cancer patients." (PMID 33411917, 2021). "Therefore, increased PLD2 expression and PA levels in MDA-MB-231 breast cancer cells were directly correlated with higher EGFR expression levels." (PMID 33832505, 2021). "Previously, we showed that nanostructures 1/2 reduced the exogenous EGFR level by more than 60% at a concentration of 200 nM after 48 h using DFA (EGFR-EGFP/RFP dual fluorescence assay) performed in MCF-7 (breast cancer), A431 (squamous carcinoma), and HeLa (cervical carcinoma) cells." (PMID 34064412, 2021).
breast carcinoma (continued). "EVs modified with GE11 peptide, a synthetic peptide that binds specifically to EGFR, could efficiently deliver let-7a miRNA to EGFR-expressing xenograft breast cancer tissues in mice, leading to a marked inhibition of tumor growth." (PMID 34326688, 2021). "Multiple evidence has shown crosstalk between PRLR and EGFR signaling pathways in breast cancer." (PMID 34572912, 2021). "Dimethyl melaleucate and three structurally related PTs, ursolic acid, 18α-glycyrrhetinic acid, and carbenoxolone suppress EGF mediated breast cancer proliferation through sustained inhibition of EGFR and its downstream effectors STAT3 and cyclin D1 in breast cancer lines." (PMID 34681605, 2021). "Antagonism of EGFR-mediated signalling by breast cancer CD99 suggests that CD99 depletion might be associated with the increased growth of metastases in our model." (PMID 34374417, 2021). "However, another lncRNA, TINCR, functions as a competing endogenous RNA (ceRNA) in human breast cancer, by means of upregulating EGFR expression and suppressing miR-503-5p expression." (PMID 34206026, 2021). "Moreover, it was reported that an immunoconjugate between ipilimumab and EGFR (epidermal growth factor) targeting breast cancer cells activated NK cells, and inhibited tumor cells more efficiently than each compound alone." (PMID 33810032, 2021). "Therefore, many factors have to be considered to stratify breast cancer patients who are likely to benefit from EGFR-targeted therapies in future clinical trials." (PMID 33995681, 2021). "Besides ERBB2, other potentially actionable genes that have been found to be often amplified in breast cancer, including TNBC, are NOTCH1/2/3, MYC, FGFR1/2, and EGFR, with EGFR amplification associated with poor patients outcome." (PMID 34281208, 2021). "Strikingly, viability of cells undergoing ribociclib-induced cellular senescence is maintained via engagement of EGFR signalling, which may be therapeutically exploited in both WT and mutant ERα breast cancer." (PMID 34944934, 2021). "However, a large percentage of patients with breast cancer are resistant to anti-EGFR therapies after long period of treatment with EGFR inhibitor." (PMID 33472170, 2021). "Moreover, CD73 was revealed to be a potential prognostic marker for patients with breast cancer and was found to promote breast cancer progression via regulate epidermal growth factor receptor (EGFR) level." (PMID 34149929, 2021). "Also, EVs with platelet-derived growth factor receptors fused to the GE11 peptide (EGFR specific) on their surface can specifically target EGFR-expressing xenografts in breast cancer." (PMID 34830787, 2021). "Overexpression of EGFR has been reported in 15–20% of all breast carcinomas and in 50–70% of TNBCs." (PMID 34404439, 2021). "Similarly, infigratinib-resistant breast cancer was also reported to exhibit elevated levels of EGFR." (PMID 34156519, 2021). "Therapies targeting EGFR have variable and unpredictable responses in breast cancer." (PMID 33845831, 2021). "Erlotinib could inhibit the tyrosine kinase activity of EGFR and may be a candidate drug in breast cancers with high WHSC1L1 expression." (PMID 34357103, 2021). "Our data suggest that inhibition of STAT3 may be a treatment option for patients with endocrine-resistant breast cancer through Src/EGFR/STAT3 activation." (PMID 34407787, 2021). "Transmembrane glycoprotein mucin 1 (MUC1), nucleoli, and epidermal growth factor receptor (EGFR) are frequently used markers in the electrochemical detection of breast cancer cells, which have been proven to be highly overexpressed on the surfaces of breast cancer cells." (PMID 34360949, 2021). "This exosome can target both human EGFR 2 of breast cancer cells and CD3 T cells." (PMID 34677212, 2021). "In a sample of 175 breast cancer cases, there was EGFR amplification in 11 of them." (PMID 34746770, 2021).
breast carcinoma (continued). "However, anti-EGFR treatments have shown limited response rates in breast cancer 29-31, possibly due to the heavy pretreatment mixed subgroups of unselected breast cancer patients." (PMID 33995681, 2021). "EGFR, which is overexpressed in approximately 30% of human primary tumors, is correlated with nodal status, tumor size, histological grade, Ki-67 index, ER/PR status, and prognosis in breast cancer, and has been a target of anti-cancer drugs." (PMID 34591414, 2021). "Moreover, breast cancer cells treated with NAC have shown attenuated hypoxia-mediated activation of EGFR and less migration capacity under hypoxic conditions." (PMID 33572626, 2021). "Additionally, nuclear PKM2 was shown to play a key role in breast cancer cell proliferation and angiogenesis through modulation of epidermal growth factor receptor (EGFR) signaling and its downstream miR-148a and miR-152 genes." (PMID 33503959, 2021). "Remarkably, this device could be used to identify single CTCs exhibiting multiple phenotypes in the early (CK8/18, EGFR) and advanced stages (Her2, EGFR) of breast cancer." (PMID 33803846, 2021). "Breast cancer cells expressing the chondroitin sulfate proteoglycan member versican G3-domain exhibit enhanced migration and invasion to primary bone stromal cells or osteoblasts in part via the epidermal growth factor receptor (EGFR)/AKT axis." (PMID 34064589, 2021). "Furthermore, CD73 expression on T-47D human breast cancer cells potentiates metastasis of breast cancer by increased expression of the epidermal growth factor receptor (EGFR) and IL-8 through the improved formation of adenosine." (PMID 32902664, 2021). "Hence, a rational choice of treatment for EGFR-expressing breast cancers would be to inhibit the EGFR-driven autocrine pathway." (PMID 34443820, 2021). "In another work, by examining EGFR trajectories in seven breast epithelial cell lines, we developed a physical phenotyping assay termed Transmembrane Receptor Dynamics (TReD) that can assess the metastatic potential of breast cancer cells." (PMID 34390568, 2021). "Strikingly, viability of cells undergoing ribociclib-induced cellular senescence is maintained via engagement of EGFR signalling, which may be therapeutically exploited in both wildtype and mutant ERα-positive breast cancer." (PMID 34944934, 2021). "In addition, it has been demonstrated to perturb tumor angiogenesis, to elicit apoptosis in a squamous cell carcinoma model, to induce mitophagy and to confine the metastatic spreading of breast carcinoma cells through the down-regulation of EGFR activity." (PMID 33924197, 2021). "BT-20 is another breast cancer cell line known to express EGFR at a high level." (PMID 35052426, 2021). "HER2 targeting is a well-accepted treatment regimen for HER2 positive breast cancer, and HER1/EGFR targeting is commonly used in head and neck squamous cell carcinoma (HNSCC), where overexpression of EGFR occurs in 80% to 90% of tumors and is similarly associated with poor outcomes." (PMID 34628733, 2021). "However, the prognostic and predictive value of EGFR and EGFR-ligands in blood has only been investigated in highly selected subsets of breast cancer patients and most studies were small." (PMID 33356806, 2021). "Efficacy and limitations of targeted therapies for LM from EGFR-mutant and ALK-rearranged NSCLC, HER2-positive breast cancer and BRAF-mutated melanomas are reported, including the use of intrathecal administration or modification of traditional cytotoxic compounds." (PMID 34207653, 2021). "MCF7 cells have been described as relatively low in EGFR expression among breast cancer cell lines." (PMID 34884742, 2021).
breast carcinoma (continued). "As chloroquine (CQ), together with primaquine, is the first-line treatment recommended for malaria and has been reported to promote anticancer activity and regulate the endocytosis-mediated degradation of EGFR, we assessed the effects of CQ on breast cancer apoptosis." (PMID 34884765, 2021). "EGFR mutation or/and deregulated expression is a hallmark of multiple human malignancies, though not common in breast cancer except in the case of TN and Basal-like cancers." (PMID 34828291, 2021). "Therefore, our interpretation in our previous study was that AREG indirectly confers trastuzumab resistance via EGFR activation in HER2-positive breast cancer." (PMID 34893673, 2021). "In the I-SPY 2 neoadjuvant trial, phospho-EGFR (Y1068, Y1173, or Y992), HER2 total, phospho-HER2 (Y1248), and phospho-Shc (Y317) were associated with pCR and recognized as predictive biomarkers for neratinib treatment in patients with breast cancer." (PMID 34203351, 2021). "In this study, multivariate analysis was performed to identify whether genotypes or alleles of BBC3 rs2032809 and EGFR rs2227983 polymorphisms are independent prognostic factors for OS, PFS and MFS in patients with breast cancer." (PMID 34441352, 2021). "Pyrotinib is a newly-developed irreversible pan-ErbB (erythroblastic leukemia viral oncogene homolog) receptor oral tyrosine kinase inhibitor (TKI) with promising efficacy in the human epidermal growth factor receptor-2 (HER2) positive breast cancer." (PMID 34422652, 2021). "In particular, in breast cancer, cell migration is potentiated through maintaining epidermal growth factor receptor (EGFR) stability and activating EGFR/P38 signaling, whereas in gastric cancer cells the MICAL2/MRTF-A complex promotes migration through the CDC42 pathway." (PMID 34946600, 2021). "Copy number (CN) alterations in ctDNA were also associated with breast cancer subtype, with CN alterations in MYC, PIK3CA, EGFR, CCNE1, CDK6, BRAF and MET more common in TNBC (q = 0.01, q < 0.0001, q = 0.001, q < 0.0001, q = 0.0003, q = 0.0002 and q = 0.01, respectively)." (PMID 33893289, 2021). "Interestingly, our observations of 17-AAG induced ErbB2 downregulation from 5 ErbB2-positive breast cancer cell lines imply similar molecular features much akin to the endocytic degradation of EGFR." (PMID 32327714, 2020). "In addition, EGFR inhibition and the presence of E2 resulted in important morphological changes both in MDA-MB-231 and shERβ MDA-MB-231 cells, suggesting the significance of EGFR signaling in the modulation of breast cancer cell morphological characteristics." (PMID 33050027, 2020). "In this study, MCF-7 breast cancer cells enriched in phosphorylated EGFR and HER2, cultured in a pro- (LPS + INF-γ) or conflicting- (LPS + INF-γ + IL-4) inflammatory environment, released EVs that increased the survival and viability of primary human monocytes." (PMID 33143170, 2020). "Here we show that in multiple HER2+ and/or EGFR+ breast cancer cell lines these AP-1-dependent tumorigenic properties of TGFβ critically rely on epidermal growth factor receptor (EGFR) activation and expression of the ΔN isoform of transcriptional regulator p63." (PMID 32350443, 2020). "Five different QDs (QD525, QD565, QD605, QD655, QD705) conjugated with antibodies against HER2, ER, PR, EGFR, and mTOR biomarkers, respectively, were used for multiplexed detection of these antigens in breast cancer cells (MCF-7 and BT474 cell lines) and in tumour biopsy specimens." (PMID 33276535, 2020). "In addition, AMPK sustains the activation of oncogenic protein kinase B (AKT) signaling upon stress or epidermal growth factor receptor (EGFR) engagement in breast cancers." (PMID 32807225, 2020). "Our findings may, therefore, be of importance for therapy of patients with breast cancers with an activated EGFR-RAS-RAF pathway." (PMID 32350443, 2020). "In breast cancer cells, a contextual synthetic lethality may exist between combined EGFR and PARP inhibitors." (PMID 32093123, 2020).